ADAMTS7 (ADAM metallopeptidase with thrombospondin type 1 motif 7)
Description:
Metalloprotease. Was previously shown to degrade COMP. However, a later study found no activity against COMP.
Synonyms: ADAM-TS 7; ADAM-TS7; ADAMTS-7; DKFZp434H204
Tractability: Antibody: UniProt places it where antibodies can reach, with medium confidence; UniProt predicts a signal peptide or a membrane-spanning region; its Gene Ontology location is reachable by antibodies, with medium confidence.
Target class: Enzyme; Hydrolase
Chemical probes: BAY-9835 (high quality)
Gene: Protein-coding gene on chromosome 15 (78,759,204 to 78,811,503, reverse strand). Ensembl gene ENSG00000136378.
Subcellular location: Secreted, extracellular space, extracellular matrix
Subcellular location (Human Protein Atlas): Vesicles; Predicted to be secreted
Pathways (Reactome):
Disease: Defective B3GALTL causes PpS
Metabolism of proteins: O-glycosylation of TSR domain-containing proteins
Gene Ontology:
Molecular function: metalloendopeptidase activity; protein binding; metallopeptidase activity
Biological process: cellular response to BMP stimulus; cellular response to interleukin-1; cellular response to tumor necrosis factor; negative regulation of chondrocyte differentiation; protein catabolic process; extracellular matrix organization; proteolysis; chondrocyte differentiation; collagen fibril organization; ossification; ossification involved in bone maturation; proteoglycan metabolic process
Cellular component: endoplasmic reticulum lumen; extracellular matrix; cell surface
Genetic constraint (gnomAD): Loss-of-function variants: 92 observed, 143.69 expected, observed/expected ratio (o/e) 0.64, 90% interval 0.54 to 0.76. The upper end of that interval is the gene's LOEUF score, 0.76, which puts it in group 3 of 6, group 1 being the genes least tolerant of losing a copy. Missense variants: 1,972 observed, 2,102.1 expected, observed/expected ratio (o/e) 0.94, 90% interval 0.9 to 0.97. Synonymous variants: 885 observed, 836.22 expected, observed/expected ratio (o/e) 1.06, 90% interval 1 to 1.12.
Homologues: Orthologues: macaque ADAMTS7 (96% identical), rabbit ADAMTS7 (81% identical), dog ADAMTS7 (78% identical), pig ADAMTS7 (74% identical), mouse Adamts7 (72% identical), rat Adamts7 (69% identical), guinea pig ADAMTS7 (67% identical), chimpanzee ADAMTS7 (54% identical), tropical clawed frog adamts7 (54% identical), zebrafish adamts7 (48% identical). Paralogues in human: ADAMTS12 (43% identical), ADAMTS9 (26% identical), ADAMTS6 (26% identical), ADAMTS18 (25% identical), ADAMTS16 (25% identical), ADAMTS20 (24% identical), ADAMTS10 (24% identical), ADAMTS19 (21% identical), ADAMTS2 (21% identical), ADAMTS17 (20% identical), ADAMTS14 (20% identical), ADAMTS3 (20% identical), and 13 more.
Diseases named in the same sentence as ADAMTS7 in open-access papers:
ADAMTS7 is named in the same sentence as 66 diseases in open-access papers, as found by Europe PMC text mining. Sharing a sentence is not in itself a finding about the gene and the disease. The quoted sentences say what the papers report.
atherosclerosis (32 papers, 2014 to 2026). A disease characterized by the build-up of fatty material and calcium deposition in the arterial wall resulting in partial or complete occlusion of the arterial lumen. "Individuals carrying protective SNPs, rs7178051 and rs3825807, exhibit reduced ADAMTS7 expression, which is linked to lower atherosclerosis risk." (PMID 39964583, 2025). "Another perspective of atherosclerosis development consists of the genes involved in plaque formation, being the extracellular matrix protease ADAMTS-7, encoded by the ADAMTS7 gene, the strongest loci associated with CAD risk." (PMID 40864779, 2025). "For instance, ADAMTS7 has been identified as a risk locus for coronary heart disease and has been shown to induce atherosclerosis through mouse experiments." (PMID 39960900, 2025). "ADAMTS13 is associated with thrombotic thrombocytopenic purpura, ADAMTS5 with osteoarthritis, and ADAMTS7 is associated with atherosclerosis and coronary artery disease." (PMID 39329961, 2024). "Here, we sought to identify molecular mechanisms and downstream targets of ADAMTS-7 mediating risk of atherosclerosis." (PMID 37675562, 2023). "ADAMTS-7 represents a novel CAD risk factor but its functional role in atherosclerosis and CAD remains incompletely understood." (PMID 37675562, 2023). "While the association of ADAMTS-7 with atherosclerosis has been clearly demonstrated in genetic studies in humans and experimental studies in mice, the molecular mechanism remained elusive." (PMID 37675562, 2023). "ADAMTS7 dosage and catalytic activity contribute to the atherosclerosis phenotype and are associated with coronary artery disease (CAD) risk." (PMID 35503474, 2022). "The extracellular protease A Disintegrin-like And Metalloproteinase with Thrombospondin Motif (ADAMTS)-7 has been strongly implicated in the aetiology of atherosclerosis and coronary artery disease (CAD)." (PMID 34587841, 2021). "The extracellular protease ADAMTS-7 has been identified as a potential therapeutic target in atherosclerosis and associated diseases such as coronary artery disease (CAD)." (PMID 34587841, 2021). "Because VSMC migration is an important process in atherogenesis, it is likely that ADAMTS7 can also a contrary role in the development of atherosclerosis, the pathology underlying the vast majority of CAD." (PMID 32897244, 2020). "Although ADAMTS7 is widely recognized to intervene in the pathophysiology of atherosclerosis, the ADAMTS7 alleles specifically related to IS have yet to be elucidated." (PMID 31460868, 2019). "COMP-degrading proteinase ADAMTS-7 has been demonstrated to be involved in the pathogenesis of atherosclerosis by both human genome-wide association studies and in vivo mouse models." (PMID 29867124, 2018). "One such interaction involves ADAMTS7, a gene associated with an increased risk of atherosclerosis." (PMID 39964583, 2025). "A disintegrin and metalloproteinase with thrombospondin type I motif 7 (ADAMTS7) is a secreted metalloproteinase enzyme with proteolytic activity and has been associated with diseases including early progression of atherosclerosis, rheumatoid arthritis, and inflammation of intravertebral discs." (PMID 35503474, 2022). "The evidence for a detrimental role has accumulated over the past decade and includes 1) reduced atherosclerosis upon ablation of the Adamts7 gene in mice; 2) GWAS that show an association of ADAMTS7 SNPs with CAD and 3) immunohistochemical detection of ADAMTS-7 in human atherosclerotic plaques." (PMID 33352066, 2020). "ADAMTS-7 is a potential therapeutic target in atherosclerosis and associated diseases such as CAD." (PMID 33352066, 2020). "Because dysregulated degradation of the ECM in vascular walls is a central phenomenon in the pathophysiology of atherosclerosis in carotid arteries, ADAMTS7 might be implicated in the early stages of vascular remodelling, thus promoting thickening of the CIMT." (PMID 31460868, 2019).
atherosclerosis (continued). "In summary, ADAMTS7 promotes atherosclerosis by driving SMC foam cell formation through an AP-1/PU.1/CD36 regulatory axis." (PMID 41609669, 2026). "The deletion of ADAMTS-7 by ATS7vac protects against both restenosis and atherosclerosis in mouse models." (PMID 40823653, 2025). "The physiological roles of the metalloprotease-proteoglycan ADAMTS7, a drug target in atherosclerosis and vascular restenosis, and its homolog ADAMTS12, are undefined in the cardiovascular system." (PMID 40115634, 2025). "Nevertheless, our data can be used to design small molecule inhibitors for other pharmaceutical targets, for example ADAMTS4 and ADAMTS5 in osteoarthritis, ADAMTS7 in atherosclerosis, or ADAMTS8 in pulmonary arterial hypertension, which spare ADAMTS9." (PMID 40449594, 2025). "Manipulation of ADAMTS7 activity in the vascular wall affects smooth muscle proliferation and migration in animal models of vascular injury and disease, and an ADAMTS7 peptide vaccine showed therapeutic benefit in a mouse model of atherosclerosis." (PMID 40115634, 2025). "Motivated by the significance of ADAMTS7 in atherosclerosis, where it is now a drug target, and observation of overlapping expression in developing and adult heart valves, we investigated the role of ADAMTS7 and ADAMTS12 in cardiac valve ECM." (PMID 40115634, 2025). "The proteolytic activity of the enzyme ADAMTS7 was recently shown to enhance the progression of atherosclerosis, in line with human genetic findings suggesting that ADAMTS7 has a role in the pathophysiology of coronary heart disease." (PMID 39149096, 2024). "In conclusion, we present the development of a selective inhibitor of ADAMTS7 which provides a good basis for further optimization studies, pharmacokinetics studies and in vivo studies using models of atherosclerosis." (PMID 39149096, 2024). "Taken together, this renders an interaction between the catalytic domain of ADAMTS-7 and TIMP-1 likely to be involved in mediating risk of atherosclerosis." (PMID 37675562, 2023). "Our novel fluorogenic substrate ATS7FP7 is suitable for high throughput screening of ADAMTS-7 inhibitors, thus accelerating translational studies aiming at inhibition of ADAMTS-7 as a novel treatment for cardiovascular diseases such as atherosclerosis and CAD." (PMID 34587841, 2021). "ADAMTS-7 and -8 are attracting considerable interest owing to their implication in atherosclerosis and pulmonary arterial hypertension, respectively." (PMID 33352066, 2020). "It is essential to identify the physiological targets of ADAMTS7 to enable a causal link to be established between ADAMTS7 function and CAD/atherosclerosis." (PMID 30926607, 2019). "The ADAMTS7 rs3825807 A allele has been associated with potentiation of VSMC migration and neointimal thickening, as well as the promotion of atherosclerosis and plaque rupture." (PMID 31460868, 2019). "The ADAMTS7 rs3825807 G allele has been noted to affect ADAMTS7 maturation, while COMP cleavage and VSMC migration has been linked with subclinical atherosclerosis." (PMID 31460868, 2019). "Genome Wide Association Studies have established ADAMTS7 as a susceptibility locus for coronary artery disease (CAD) and atherosclerosis is reduced in Adamts7−/− mice." (PMID 30926607, 2019). "In the present review, we focused on the role of ADAMTS-7 in the progression of inflammatory diseases including arthritis and atherosclerosis." (PMID 26696755, 2015). "Previous studies demonstrated that ADAMTS-7 facilitates vascular muscle cell migration and intimal thickening after vascular injury and plays an important role in atherosclerosis and restenosis by degrading COMP." (PMID 25885961, 2015). "ADAMTS-7 is involved in the proliferative response to vascular injury in a way that is similar to the progressive phase of atherosclerosis." (PMID 25885961, 2015).
atherosclerosis (continued). "In addition to potential mechanistic insights into myxomatous valve disease in humans, potential translational significance of the work lies in the current consideration of ADAMTS7 as a drug target in atherosclerosis." (PMID 40115634, 2025). "In fact, however, the vast majority of data refer to the role of ADAMTS-7 as a potent risk factor for atherosclerosis, and not cardiac function." (PMID 39768861, 2024). "ADAMTS-7 is a potential target for the therapy of atherosclerosis." (PMID 36833435, 2023). "Considering the potential role of ADAMTS7 in the pathogenesis of vascular atherosclerosis, ADAMTS7 may, therefore, be a potential therapeutic target in atherosclerosis." (PMID 35053160, 2021). "In addition, ADAMTS7 is involved in the migration and proliferation of smooth muscle and the development of atherosclerosis and restenosis." (PMID 33851708, 2021). "The significance of LTBP4 proteolysis by ADAMTS-7 for atherosclerosis is also currently unclear." (PMID 33352066, 2020). "We postulated that VSMCs with the ADAMTS7 rs3825807 A variant may migrate into the endothelium of subcutaneous vessels, phagocytize oxidized LDL, and prevent the occurrence of atherosclerosis." (PMID 32897244, 2020). "Likewise, the ADAMTS7 rs3825807 GG genotype appears to have an inverse correlation with atherosclerosis, reflected in lower frequency and magnitude of carotid atherosclerosis." (PMID 31460868, 2019). "However, it is essential to identify the physiological targets of ADAMTS7 to enable a causal link to be established between ADAMTS7 functions and CAD/atherosclerosis." (PMID 31357630, 2019). "The casual link between ADAMTS-7 and atherosclerosis progression has yet to be established." (PMID 26696755, 2015). "The rs3825807 G/G genotype in the ADAMTS7 locus, has been linked with reduced prevalence and severity of atherosclerosis, yet does not appear to reduce the expression of ADAMTS7 but its maturation and activity, resulting in reduced COMP cleavage and attenuated VSMC migration." (PMID 31460868, 2019). "Therefore, ADAMTS7 could be a potential therapeutic target to treat atherosclerosis." (PMID 36833435, 2023). "In summary, ADAMTS-7 is a potential therapeutic target in CAD and related diseases resulting from atherosclerosis, but more research is needed to validate it as a target and allow a better understanding of the molecular mechanisms involved." (PMID 33352066, 2020). "Conditional KO of Adamts7 in either cell type did not reduce atherosclerosis, whereas transgenic induction in either cell type increased atherosclerosis." (PMID 41609669, 2026). "The molecular and cellular mechanisms that mediate the effect of ADAMTS7 on atherosclerosis and CHD are not entirely clear." (PMID 39149096, 2024). "Disrupting the interaction of ADAMTS-7 and TIMP-1 might be a strategy to increase collagen content and plaque stability for reduction of atherosclerosis-related events." (PMID 37675562, 2023). "Several in vitro substrates of ADAMTS-7 have been reported in the literature, but clear links with atherosclerosis and VSMC behaviour have not been established." (PMID 33352066, 2020). "It has been suggested that small molecule inhibitors of ADAMTS7 could have therapeutic potential in CAD given that Adamts7−/− mice have reduced atherosclerosis in hyperlipidemic mouse models." (PMID 30926607, 2019). "Our results do not confirm association of ABO rs579459, PPAP2B rs17114036, ADAMTS7 rs3825807, PIK3CG rs17398575, and EDNRA rs1878406 polymorphisms with subclinical atherosclerosis and CV disease in RA patients." (PMID 24795506, 2014). "In three recent GWAS studies, the variants rs4380028, rs1994016, and rs3825807 in the ADAMTS-7 gene were associated with coronary artery disease (CAD) and, even more specifically, the rs3825807 G/G genotype had a negative association with atherosclerosis prevalence and severity." (PMID 39768861, 2024).
atherosclerosis (continued). "Therefore, therapy that would decrease the expression of ADAMTS7 could potentially slow down the cleavage of COMP and decrease the migration of vascular smooth muscle cells and slow down the process of atherosclerosis." (PMID 36833435, 2023). "While the molecular and cellular mechanisms involving ADAMTS-7 in atherosclerosis have not yet been elucidated, SVEP1 degradation may be involved." (PMID 33185739, 2020). "It has been suggested that enhanced sCOMP levels result from the proteolytic activity of ADAMTS-7 (a disintegrin and metalloproteinase with thrombospondin motifs-7), which promotes the degradation of COMP in blood vessels and thus mediates vascular calcification and atherosclerosis." (PMID 31963737, 2020).
coronary artery disease (20 papers, 2014 to 2025). "Genome-wide association studies (GWAS) showed that single nucleotide polymorphisms (SNPs) in ADAMTS7 were possibly correlated to coronary artery disease." (PMID 36833435, 2023). "The ADAMTS7 gene encodes a zinc-dependent protease and has been associated with coronary artery disease in numerous GWAS." (PMID 34968759, 2022). "ADAMTS7 is a secreted metalloproteinase enzyme and proteoglycan associated with the early progression of coronary artery disease." (PMID 35503474, 2022). "In large-scale genome-wide association (GWA) investigations, variants of the ADAMTS7 gene have been related to an increased risk of coronary artery disease (CAD)." (PMID 31460868, 2019). "Several large-scale genome-wide association studies have identified single-nucleotide polymorphisms in the genomic region of A Disintegrin And Metalloproteinase with ThromboSpondin type 1 repeats (ADAMTS)-7 and associations to coronary artery disease." (PMID 28623250, 2017). "Nevertheless, a study showed an association between the ADAMTS-7 locus and angiographic coronary artery disease." (PMID 25885961, 2015). "Moreover, it has been reported that ADAMTS7 deficiency, a novel locus for coronary artery disease in humans, suppressed neointimal formation after wire injury in mice and downregulated the migration of vascular smooth muscle cells." (PMID 35224040, 2022). "Notably, TFPI rs7586970 T/C and ADAMTS7 rs3825807 A/G are both coronary artery disease (CAD) risk SNPs (p=9.00E-6, p=1.00E-12)." (PMID 32897244, 2020). "SVEP1 is a substrate of the protease ADAMTS‐7, which also include genetic variants associated with CAD and BP, and contains the linear peptide sequences Arg‐Gly‐Asp (RGD) and Leu‐Asp‐Val (LDV) sequences." (PMID 35802072, 2022). "ADAMTS7 rsrs4380028 was consistently related to coronary artery disease: both coronary artery calcification and coronary artery stenosis." (PMID 32411445, 2020). "This was the first large-scale human study to translate the previous laboratory findings back to the clinic, and it rendered ADAMTS-7 as a possible factor that may be involved in the severity of coronary artery disease." (PMID 39768861, 2024).